DLL1 (delta like canonical Notch ligand 1)
Diseases named in the same sentence as DLL1 in open-access papers (continued):
Sharing a sentence is not in itself a finding about the gene and the disease.
tumor (continued). "Most notably, pharmacological blocking of Dll1 or NF-κB pathway sensitizes tumor cells to chemotherapy and significantly abolishes tumor growth and metastasis in tumor initiation and progression study." (PMID 33462238, 2021). "In this tumor initiation and progression study, Dll1 antibody alone had a modest inhibitory effect on tumor growth, whereas, the combination treatment dramatically reduced tumor growth, suggesting that Dll1-blocking sensitizes Dll1+ TICs to chemotherapy." (PMID 33462238, 2021). "The observation that DLL1 downregulation induces apoptosis of MCF-7 cells prompted us to next evaluate apoptosis in tumor sections, using the TUNEL method." (PMID 34439228, 2021). "Mechanistically, we showed that Dll1+ tumor cells resist chemotherapy by avoiding drug-induced cell death and DNA damage as seen by cleaved-caspase-3 assay, γH2AX staining, TUNEL and cell cycle assays." (PMID 33462238, 2021). "We found that Dll1+ cells increase dramatically from normal mammary gland to hyperplasia and tumor, suggesting a tumor supporting function of Dll1." (PMID 33462238, 2021). "An in vitro tumorsphere assay with Dll1+ tumor cells demonstrated a significant decrease in the number and size of tumorspheres with a combination treatment of IMD and doxorubicin, similar to effects seen with Dll1-blocking antibody and doxorubicin." (PMID 33462238, 2021). "Since NF-kB was found to be downstream of Dll1-mediated Notch signaling, we next sought to determine if the NF-kB inhibitor IMD-0354 (IMD) would resensitize tumor cells to chemotherapy, phenocopying the effect of the Dll1-blocking antibody." (PMID 33462238, 2021). "On the other hand, CD11c-specific deletion of DLL1 resulted in accelerated tumor growth in murine tumor models coupled to a reduction in CD8+ T cell activation and reduced differentiation of antigen-specific cytotoxic T cells and memory cells." (PMID 32922403, 2020). "Compared to age-matched controls, tumor-bearing mice have low DLL1 and DLL4 expression levels in bone marrow cells as well as low splenic T:B cell ratios." (PMID 32922403, 2020). "This is in line with an earlier study that selective stimulation of Dll1-Notch signaling in T cells rescued T cell function and inhibited tumor growth." (PMID 33585446, 2020). "We further tested the effect of interference with DLL1-mediated Notch activation on the induction of T-cell cytotoxic responses using the sDLL1 construct in the non-tumor context of a cardiac allograft rejection." (PMID 30940183, 2019). "To evaluate the roles of Notch ligands DLL1 and Jag2 expression on DCs in the regulation of T-cell-mediated anti-tumor immunity, we generated mice with CD11c-lineage-specific deletion of their genes." (PMID 30940183, 2019). "Clustered DLL1 treatments significantly reduced tumor growth and prolonged survival in both wild-type and DC-specific Dll1−/− animals." (PMID 30940183, 2019). "Deficiency in DLL1 expression in DCs resulted in a significant reduction of CD8+ T-cell activation, tumor antigen-specific CTL and differentiation of central memory CD8+CD44+CD62L+ T-cell populations." (PMID 30940183, 2019). "Deletion of Dll1 in DCs also had a significant effect on CD8+ T-cells that resulted in their decreased activation in the tumor as shown by decreased expression of CD25 and CD44." (PMID 30940183, 2019). "In contrast, expression of DLL1 or DLL4 in DC was positively correlated with the expression of Notch receptors on tumor-infiltrating Tem cells." (PMID 30940183, 2019). "The expression of BCCIP, a gene suggested to suppress tumor initiation but required for tumor progression, was reduced by 2-fold upon DLL1 downregulation." (PMID 31107884, 2019). "In complementary experiments, we next tested if increasing DLL1 expression in luminal cells further augments tumor growth and metastasis." (PMID 30442981, 2019).
tumor (continued). "We made a similar observation with another luminal cell line T47D, demonstrating that DLL1 knockdown tumor cells (KD1 and KD2) had slower growth compared to control." (PMID 30442981, 2019). "Conversely, interference with ligand specific signaling by monovalent soluble JAG1 or soluble DLL1 efficiently improved anti-tumor immunity or blocked anti-tumor and allogeneic T-cell responses, respectively." (PMID 30940183, 2019). "Our data show that presentation of DLL1 by DCs is indispensable for the induction of anti-tumor T-cell responses." (PMID 30940183, 2019). "On the other hand, a decline was noted in the proportions of CD68+MHCII+F4/80+ M1 and CD68+MHCII+CD86+CD206+ M2 macrophages in the tumor-infiltrate and spleen of Dll1-ablated mice." (PMID 30940183, 2019). "The results imply that the adequate expression of DLL1 in DCs is a prerequisite for eliciting effector T-cells and efficient anti-tumor responses." (PMID 30940183, 2019). "As in the human MCF7 luminal cell line, we found that overexpression of Dll1 leads to increased tumor growth of WTB cells." (PMID 30442981, 2019). "The regulators of transcription and differentiation, ASCL1 and DLL1 in the Notch signalling pathway, were found to be up-regulated in the mtDNA-depleted tumours but down-regulated in the cells." (PMID 30208958, 2018). "Reduced expression of DLL1/4 in the bone marrow of tumor bearing mice inversely correlated with increased VEGF levels in one study." (PMID 30967879, 2018). "In the present study, we semi-quantified the levels of DLL1 protein in the same set of the tumor tissues in mice via immuno-histological analysis." (PMID 28281638, 2017). "Dll1 and Dll3 seemed less expressed in the tumor epithelium, and Dll4, all Notch receptors, and Hes1 seemed upregulated." (PMID 28086833, 2017). "Recent studies indicate that ADAM10 is involved in the cleavage of a number of proteins such as the NOTCH receptor, its ligand DLL1 and other proteins influencing the metastatic potential of tumor cells through EMT (N-cadherin, E-cadherin, B-catenin)." (PMID 27888801, 2017). "Both the role and mechanism of the DLL1 gene in the context of OS chemoresistance were systematically investigated in cultured cells and tumor xenografts in nude mice." (PMID 28281638, 2017). "While overexpression of Dll4 was shown to promote tumor growth, overexpression of a soluble DSL domain of Dll1 resulted in reduced tumor growth by attenuating vascularization." (PMID 26713603, 2016). "By qPCR we next examined the expression of NOTCH1 and DLL1 in a subset comprising 12 tumor tissues (4 at stage I, 4 at stage II and 4 at stage III) and 6 normal samples, where three were in the proliferative phase and three in secretory phase." (PMID 27039384, 2016). "It is proved that DLL1 was highly correlated with tumor'growth and differentiation, our previously study showed that DLL1 was associated with MDR in small cell lung cancer (SCLC)." (PMID 23769341, 2013). "There was a substantial increase in Dll1 protein levels in the tumor compared to the healthy cerebellum." (PMID 21931765, 2011). "Additionally, intrinsic NOTCH1 signaling in RT is induced by CD4+ T cells expressing Delta-like protein 1 (Dll1) in the tumor microenvironment (TME), highlighting the importance role of the environmental immune cells in RT." (PMID 40565027, 2025). "IFN-γ can hinder tumor angiogenesis through targeting the Notch-Dll4/Dll1 pathways or integrins." (PMID 40370455, 2025). "Additionally, knocking down Ndrg1 in BLM tumor organoids reduced secretory progenitor marker gene expression (Sox4, Atoh1, Dll1, Notch1), but increased enterocyte marker gene expression (Cdhr2, Aqp8)." (PMID 38893159, 2024). "Indeed, Dll1 was upregulated on cDCs sorted from IL-38 neutralized versus control tumors compared with other cells in the tumor microenvironment." (PMID 39209451, 2024). "Therefore, it also indirectly proved that DLL1 has great potential in tumor therapy of the formation of blood vessels." (PMID 36071128, 2022).
tumor (continued). "In line with CTCDOs enhanced aggressiveness and tumor-forming capacity, we found an increased expression of several factors implicated in stemness maintenance both in normal and malignant tissues such as PDX1, Goosecoid, Oct3/4, SOX2, DLL1, Cited-2." (PMID 35260172, 2022). "Furthermore, the effects of LNT on tumor growth were mediated with neutrophils, which is different from DLL1 and commonly used cancer immunotherapy, such as immune checkpoint inhibitors, which activate T cells." (PMID 36008793, 2022). "Moreover, elevated DLL1 in the tumor microenvironment (TME) upregulated transcription of granzyme B and interferon γ (IFN-γ) and slowed down the growth of breast and lung tumors." (PMID 36008793, 2022). "It is possible that Dll1 may have tumor-promoting function in other basal tumors, which needs further explorations." (PMID 33462238, 2021). "To functionally test whether Dll1+ cells are resistant to doxorubicin in the PyMT-Dll1mCh reporter model, we sorted out Dll1+ and Dll1- tumor cells and treated them in vitro with doxorubicin." (PMID 33462238, 2021). "Accordingly, it is conceivable that targeting murine DLL1, namely in the tumor microenvironment, could also account for the anti-tumorigenic effects herein observed in the MCF-7 xenograft mouse model." (PMID 34439228, 2021). "Together, these observations suggest that Dll1-mediated Notch signaling induces activation of NF-kB signaling by regulating NF-kB1, which may contribute to tumor cell survival." (PMID 33462238, 2021). "Previous studies have shown that DLL1 plays a critical role in tumor angiogenesis." (PMID 34439228, 2021). "We found that Dll1+ tumor cells are resistant to the chemotherapeutic drug, doxorubicin." (PMID 33462238, 2021). "Moreover, recently, DLL1+ cells have been shown to bear similarities to CSCs by showing a high tumor-initiating capacity as well as the ability to drive metastasis and chemoresistance in aggressive luminal breast tumors." (PMID 34439228, 2021). "Notably, our recent studies highlighted the tumor-promoting function of the Notch ligand Dll1 in luminal breast cancer." (PMID 33462238, 2021). "In this study, we developed and characterized a novel specific anti-DLL1 antibody with efficacy in inhibiting BC cell proliferation, mammosphere formation and angiogenesis, as well as anti-tumor and anti-metastatic efficacy in an ER+ BC mouse model without side effects." (PMID 34439228, 2021). "Finally, γH2AX staining (green staining indicates DNA damage) shows reduced doxorubicin-induced DNA damage in Dll1+ tumor cells compared to Dll1− tumors, potentially explaining the chemotherapeutic resistance of Dll1+ tumors." (PMID 33462238, 2021). "Thus, our results suggest that activation of NF-kB downstream of Dll1 signaling in tumor cells promotes chemoresistance and blocking all these components together can lead to significant response in thes tumors." (PMID 33462238, 2021). "Furthermore, combination treatment targeting Dll1, NF-kB and doxorubicin significantly abolished tumor growth of Dll1+ tumor cells." (PMID 33462238, 2021). "Dll1 expression was significantly downregulated in tumor cells of PyMT-Dll1cKO mice." (PMID 33462238, 2021). "Pharmacological blocking of Dll1 can reactivate tumor cells sensitive to chemotherapy." (PMID 34374886, 2021). "Furthermore, increased nuclear translocation of NF-κB was observed in tumor cells expressing higher levels of Dll1." (PMID 33462238, 2021). "Finally, we also found increase in metastasis signature to be enriched in Dll1+ tumor cells, supporting our in vivo metastasis data." (PMID 33462238, 2021). "Next, we found activation of NF-κB, hypoxia and Notch pathways enriched in Dll1+ tumor cells, which may contribute to the chemoresistance." (PMID 33462238, 2021). "Collectively, these results show that anti-DLL1 Dl1.72 inhibits tumor growth and is well tolerated." (PMID 34439228, 2021).
tumor (continued). "However, there was a relative increase in the number of Dll1+ luminal (K8+) cells when compared to Dll1+ basal tumor cells (K14+ and K5+) as tumors progressed from hyperplasia stage to late tumor." (PMID 33462238, 2021). "In addition, Met-1 tumor cells from obese mice expressed significantly higher expression of CSC-associated genes Sox2 and Notch Receptor 2 (Notch2), as well as Notch ligand Dll1 and downstream regulator Dtx2." (PMID 32098183, 2020). "Indeed, systemic DLL-1 administration in a murine lung cancer model increased T cell infiltration into tumours, as well as, elevating memory T cells, decreasing Treg cells and limiting tumour vascularisation." (PMID 32575680, 2020). "Moreover, differentiated cells within the tumor express higher levels of Dll1 compared to GSCs, contributing to Notch signaling activation in GSCs." (PMID 30832246, 2019). "Our finding showed that NOTCH1 and DLL1 are both highly expressed in tumor cells." (PMID 31118022, 2019). "Conditional deletion of Dll1 in retinal myeloid cells resulted in increased number of TC and increased filopodia, along with increased vascular density and branching, consistent with studies in tumours, in which Dll1 overexpression leads to reduced angiogenesis." (PMID 31278348, 2019). "Moreover, LLC tumor-bearing wild-type mice treated with sDLL1 significantly increased tumor growth, similar to accelerated tumor growth seen in DC-specific Dll1−/− mice." (PMID 30940183, 2019). "Tumor growth was significantly enhanced in MCF7 DLL1-OE compared to empty vector control." (PMID 30442981, 2019). "Based on our findings at the mRNA levels, it is possible that DLL1, whose expression was elevated in MSCs by TNFα and IL-1β stimulation (through a p65-mediated pathway, as analyzed for TNFα stimulation), is a partner of tumor cell-expressed Notch1." (PMID 31105691, 2019). "Our data suggest a supporting role for DLL1 in promoting tumor cell proliferation and angiogenesis." (PMID 30442981, 2019). "We found that both WTB and MCF7 Dll1-KD tumors showed a significant decrease in Ki67+ cells compared to control tumors, suggesting that decreased proliferation accounts in part for the slower tumor growth." (PMID 30442981, 2019). "DC lineage-specific genetic ablation or systemic blockade of DLL1-Notch interaction, as shown in this study, resulted in accelerated tumor growth in the tested lung and pancreatic tumor models, likely due to insufficient DLL1 signaling and consequent impairment of anti-tumor immune responses." (PMID 30940183, 2019). "Soluble DLL1 can prevent allograft rejection, whereas clustered DLL1 can substitute in large part for inadequate presentation of DLL1 by DCs needed for proper T-cell stimulation, and elicit anti-tumor responses to reject tumors." (PMID 30940183, 2019). "For instance, a higher expression of ASCL1, Dll1, Notch1, -3, -4, and Hey1 correlates with a higher glioma grade and a worse prognosis, indicating that more activated Notch signaling promotes a more undifferentiated and aggressive tumor phenotype." (PMID 30832246, 2019). "Thus, pharmacological or genetic disruption of DLL1-Notch interaction decreased T-cell proliferation, IFN-γ production and anti-tumor T-cell function, confirming the critical requirement for DLL1-Notch signaling for DC-supported T-cell function." (PMID 30940183, 2019). "Altogether, the results point to a functional axis of DLL4/DLL1 and Notch1/Notch2 as an essential element in DC-T-cell interactions needed for the induction of effector T-cell differentiation and eliciting T-cell-mediated anti-tumor immunity." (PMID 30940183, 2019). "Concerning the microenvironment involvement, Notch signaling may be triggered also by BMSC-derived Dll1, resulting in increased MM cell clonogenic growth in vitro and tumor burden in 5T33MM syngeneic murine model." (PMID 30873026, 2019). "DLL1 over-expression has been shown to attenuate tumor vascularization." (PMID 30635008, 2019).
tumor (continued). "Conversely, the selective activation of Dll1-mediated Notch signaling in BM precursors in tumor-bearing mice resulted in the increase of tumor-infiltrating T cells and enhanced activation of Th1-type IFNγ-producing T cells, resulting in tumor growth inhibition." (PMID 30154786, 2018). "Constitutive expression of DLL1 on bone marrow and dendritic cells was also reported to enhance T-cell infiltration into tumors, suppress tumor growth and increase the survival of mice transplanted with murine tumor cell lines [Lewis Lung Carcinoma (LLC), D459 Fibrosarcoma, and EL4 T cell Lymphoma]." (PMID 30967879, 2018). "Moreover, therapeutic administration of a multivalent, clustered form of DLL1 (c-DLL1) arrested tumor growth and prolonged survival of mice transplanted with LLCs or D459 tumor cells." (PMID 30967879, 2018). "MDSC isolated from the tumor site have decreased DLL1/4 and increased Jagged1/2 expression." (PMID 30967879, 2018). "We observed that tumor-induced decrease in the expression of Notch receptors, Notch1, Notch2, Notch3 and Notch4, as well as ligands Dll1, Dll4 and Jagged1 in splenocytes of 4T1HA and RencaHA tumor-bearing mice could be reversed by treatment with bortezomib." (PMID 26431276, 2015). "The hypoxia-Notch gene subset (HIF-1α/PGK1/VEGF/CA9/OPN-Notch1/Dll1/Hes1/Hes6/Hey1/Hey2) identified by us might hold prognostic implication and offer new opportunities in tumor sub-classification and targeted therapy." (PMID 25734817, 2015). "NOTCH1 and its ligand, DLL1, were expressed at plasma membranes and in the cytoplasm of cells in the upper normal urothelium layer, but became downregulated in UC tissues, especially in high-stage tumours." (PMID 25167871, 2014). "In addition to downregulation, we frequently observed delocalization of NOTCH1 and DLL1 to the cytoplasm in tumour cells." (PMID 25167871, 2014). "Additionally, Huang and colleagues highlighted that augmented release of Delta-like 1 (DLL1) in the TME gave rise to durable vascular normalization to diminish tumor hypoxia and facilitated the infiltration of CD8+ T cells as well as the polarization of M1-phenotypic TAMs." (PMID 36439137, 2022). "Moreover, Dll1+ tumor cells are enriched for stem cell genes and as expected, the Dll1+ cells showed reduced expression of cell cycling genes, while Dll1− cells were highly enriched, highlighting the relative quiescent properties of Dll1+ tumor cells, which is confirmed by EdU assay." (PMID 33462238, 2021). "Data showing that DLL1+ BC tumor cells display CSC characteristics, together with our findings showing that DLL1 controls the expression of SOX9, supports the importance of these studies, which may provide additional insights into the mechanisms underlying DLL1’s key oncogenic role in BC." (PMID 34439228, 2021). "However, overall, it is apparent that hypoxic gliomaspheres mimic the in-vivo tumor condition better than the other tissue culture model as the upregulation of Notch genes (Notch1, Notch2, Notch3, Dll1, Hes1, Hey1 and Hey2) is further enhanced upon exposure to hypoxia." (PMID 25734817, 2015). "Interestingly, Notch-1 and Dll1 were specifically up-regulated in residual tumors compared to untreated primary tumors, disseminated cells, or metastases, suggesting a unique role for these genes in residual tumor biology." (PMID 23520493, 2013). "As human NK cells mature, Dll1-mediated Notch signaling is activated to promote the expression of CD16 and killer Ig-like receptors (KIRs), resulting in cytotoxicity against tumor cells." (PMID 37131214, 2023). "Among these ligands, DLL1 and DLL4 have been identified as key regulators of tumor angiogenesis, making them promising therapeutic targets." (PMID 37907742, 2023).